MAVS (mitochondrial antiviral signaling protein)
Diseases named in the same sentence as MAVS in open-access papers (continued):
Sharing a sentence is not in itself a finding about the gene and the disease.
AIDS (2 papers, 2024 to 2025). A syndrome resulting from the acquired deficiency of cellular immunity caused by the human immunodeficiency virus (HIV). "Conversely, individuals with the AA genotype of MAVS rs867335 were associated with a later clinical stage of AIDS compared to those with the AT genotype (p = 0.042, OR = 2.300, 95% CI 1.012–5.226)." (PMID 40331958, 2025). "Three SNPs (OAS1 rs1131454, NLRP3 rs10754558, and MAVS rs867335) were found to be related to the clinical staging of AIDS." (PMID 40331958, 2025). "The number of months of AIDS-free untreated follow up was comparable between B*57-LTNPs and non-B*57 LTNP but B*57-LTNP had a significant longer AIDS-free follow up than progressors (p = 0.001) and MAVS-/- (p = 0.02)." (PMID 39356699, 2024).
cervical cancer (2 papers, 2019 to 2020). A primary or metastatic malignant neoplasm involving the cervix. "Promoter methylation status of cyclic GMP-AMP synthase (cGAS)/mitochondrial antiviral-signaling (MAVS)/tumor necrosis factor receptor-associated factor 3 (TRAF3) in control, cervical precancerous lesion (CPL), and cervical cancer (CC)." (PMID 31803230, 2019). "Association analysis of the promoter methylation level of cyclic GMP-AMP synthase (cGAS)/mitochondrial antiviral-signaling (MAVS)/tumor necrosis factor receptor-associated factor 3 (TRAF3) gene with the risk on cervical precancerous lesion (CPL), and cervical cancer (CC)." (PMID 31803230, 2019).
chronic kidney disease (2 papers, 2022 to 2023). Impairment of the renal function secondary to chronic kidney damage persisting for three or more months. "Besides, MAVS was also downregulated in the injured hearts associated with the advanced chronic kidney disease caused by 5/6 nephrectomy (Nx)." (PMID 35844503, 2022).
colon adenocarcinoma (2 papers, 2016 to 2024). "MAVS knockdown in WiDr human colon adenocarcinoma cells also conferred radioresistance." (PMID 27034163, 2016).
colon carcinoma (2 papers, 2021 to 2022). "Another study also showed that antiviral immune response mediated by MAVS complex is opposed by SARS-CoV-2 nucleocapsid protein (NP), SARS-CoV-2-NP, to facilitate NP-mediated immune evasion in on colon cancer cell line CaCo-268." (PMID 35970857, 2022).
dengue (2 papers, 2016 to 2022). "The anti-malarial hydroxychloroquine is an autophagy inhibitor, and in vitro testing has demonstrated inhibition of dengue virus infection via induction of reactive oxygen species and mitochondrial antiviral signaling protein." (PMID 26934531, 2016). "In the infected cells, dengue circumvents antiviral signaling at multiple levels: through evasion of viral RNA sensing, interference of retinoic acid-inducible gene (RIG-I) and mitochondrial antiviral-signaling (MAVS) protein and cGAS/STING pathways, and interference with interferon signaling." (PMID 36197108, 2022).
Fever (2 papers, 2019 to 2021). Body temperature elevated above the normal range. "The OROV fever pathogenesis was in fact described as restricted by the IFN pathway-related signaling molecules MAVS, IRF-3, IRF-7 in non-myeloid cells." (PMID 31784575, 2019).
Hepatitis (2 papers, 2021 to 2025). Inflammation of the liver. "Additionally, intrinsic apoptosis mediated by MAVS signaling appears to be responsible for hepatitis in a murine model of HAV infection." (PMID 34066709, 2021). "Once hepatic MAVS levels’ significance in modulating diet-induced liver inflammation was established, we aimed to evaluate markers of de novo lipogenesis, fatty acid oxidation, and fatty acid uptake to ascertain if fatty acid metabolism could mediate MAVS-induced lipid load." (PMID 38761407, 2025). "Interestingly, IFNAR1-deficient mice developed hepatitis after HAV infection, but MAVS-deficient mice did not." (PMID 34066709, 2021).
Listeria monocytogenes infection (2 papers, 2014 to 2019). "Whereas in the context of Francisella tularensis and Listeria monocytogenes infection IFNAR expression was required for inflammasome activation, in our study, MAVS and not IFNAR signaling played the dominant role." (PMID 24743949, 2014).
myeloid leukemia (2 papers, 2023). A clonal proliferation of myeloid cells and their precursors in the bone marrow, peripheral blood, and spleen. "One such phosphosite, MAVS Ser222, has been reported after stimulation of human myeloid leukemia cells with TNF, which was an unexpected finding since MAVS is not known to be a part of TNF signaling pathways." (PMID 37238738, 2023).
non-small cell lung carcinoma (2 papers, 2021 to 2022). A group of at least three distinct histological types of lung cancer, including non-small cell squamous cell carcinoma, adenocarcinoma, and large cell carcinoma. "The attenuated measles virus of the Edmonston strain (MV-Edm) activates p62-mediated mitophagy in non-small-cell lung cancer (NSCLC) cells by disrupting MAVS and resulting in the significant inhibition of type I IFN responses." (PMID 33799853, 2021).
osteoarthritis (2 papers, 2018 to 2021). A noninflammatory degenerative joint disease occurring chiefly in older persons, characterized by degeneration of the articular cartilage, hypertrophy of bone at the margins and changes in the synovial membrane. "The ectopic MAVS expression caused chondrocytes apoptosis might be responsible for the development of osteoarthritis." (PMID 29392080, 2018). "To further explore the physiological role of MAVS in the development of osteoarthritis, we introduced the murine MAVS expression vector into in the mouse chondrogenic cell line ATDC5." (PMID 29392080, 2018). "This study is conducted to evaluate the role of RIG-I and its adaptor protein MAVS in the pathogenesis of osteoarthritis." (PMID 29392080, 2018). "To further investigate the role of RIG-I and MAVS in the pathogenesis of osteoarthritis, we conducted this study." (PMID 29392080, 2018).
pancreatic cancer (2 papers, 2020 to 2024). "We found that enhanced T1IFN expression by ATM inhibitor in combination with radiation was mediated by the POLIII/RIG-I/MAVS signaling pathway, independent of the canonical cGAS/STING pathway, suggesting the potential dysregulation of cGAS/STING signaling in pancreatic cancer." (PMID 38376927, 2024).
parasitemia (2 papers, 2016 to 2017). "A strong early IFN-I response, mediated by the MDA5/MAVS pathway, and increased numbers of activated macrophages in the spleen have been associated with the decline of N67 parasitemia in C57BL/6 mice." (PMID 28790316, 2017).
type 2 diabetes (2 papers, 2025). "A study analyzing gene expression between individuals with type II diabetes and controls found differential expression of the RIG‐I‐like receptor signaling pathway, highlighting the genes TBK1, ATG5, TANK, IL8, and MAVS." (PMID 40476695, 2025).
acute myeloid leukemia (1 paper, 2022). Acute myeloid leukemia (AML) is a group of neoplasms arising from precursor cells committed to the myeloid cell-line differentiation. "Two recent studies demonstrated that RIG-I activated by short 5′-triphosphate-modified RNA (ppp-RNA) reduced tumor burden in melanoma and acute myeloid leukemia (AML) model, which was dependent on CD4+ T cells, CD8+ T cells and the intact MAVS/IFN signaling in the host." (PMID 35413927, 2022).
acute myocardial infarction (1 paper, 2025). Necrosis of the myocardium, as a result of interruption of the blood supply to the area. "The miR-302/367 cluster, known to promote myocardial regeneration post-myocardial infarction, can inhibit MAVS activation by downregulating SLC25A12, a mitochondrial carrier essential for RLR signaling." (PMID 40842475, 2025).
Addison’s Disease (1 paper, 2017). "We investigated whether MAVS coding polymorphisms are associated with Addison’s disease (AD) and type 1 diabetes (T1D) in Polish population." (PMID 27652379, 2017).
Anosmia (1 paper, 2022). An inability to perceive odors. "Global analysis showed some variants associated with anosmia in IFHI1, TLR8, MAVS and TRAF3: this suggests that not only the severity of symptomatology but also even some very specific clinical manifestations depend on host genomic profiles." (PMID 36228008, 2022).
arteriosclerosis (1 paper, 2021). A vascular disorder characterized by thickening and hardening of the walls of the arteries. "RIG-I represents a stimulus for mitochondrial antiviral signaling (MAVS) capable of inducing cardiovascular calcification in human with Singleton-Merten syndrome and aortic calcium accumulation is found to be decreased in MAVS-deficient mice with arteriosclerosis." (PMID 34781960, 2021).
astrocytomas (1 paper, 2023). "Previous study proved that inhibition of adenosine-to-inosine editing could promote expression of immune response protein MAVS in GBM, and RNA editing activity was reported to inhibit cell migration and proliferation of astrocytomas." (PMID 36845382, 2023).
atherosclerosis (1 paper, 2025). A disease characterized by the build-up of fatty material and calcium deposition in the arterial wall resulting in partial or complete occlusion of the arterial lumen. "miR-33/33* inhibits AMPK signaling and indirectly reduces MAVS aggregation, impairing mitophagy and mitochondrial homeostasis—mechanisms closely linked to atherosclerosis." (PMID 40842475, 2025). "Also, MAVS is involved in the activation of the antiviral signaling pathway and inflammasome, so MAVS inhibitors can, to some extent, alleviate certain inflammatory diseases such as atherosclerosis." (PMID 40842475, 2025).
bacterial pneumonia (1 paper, 2024). Acute infection of the lung parenchyma caused by bacteria (e.g., Streptococcus pneumoniae, Haemophilus influenzae, Chlamydia pneumoniae, Mycoplasma pneumoniae, and Legionella pneumophila). "Here, we introduce an exogenously administered, DNA-like RIG-I binding partner that stimulates unanticipated RIG-I/MAVS-dependent host defense responses against viral and bacterial pneumonia." (PMID 39352770, 2024).
bone metastasis (1 paper, 2023). Transfer of a neoplasm from its primary site to bones. "While developing an OS predictive model for patients with bone metastasis, we observed that MAVS acted as a prognostic protective factor while other IRGs acted as prognostic risk factors." (PMID 37494663, 2023).
breast invasive carcinoma (1 paper, 2024). "Specifically, DDX58, C6orf150, IKBKE, TBK1, and IRF3 exhibited a pronounced increase in breast invasive carcinoma (BRCA), while MAVS and TMEM173 expression was significantly lower in BRCA compared to normal controls." (PMID 38817870, 2024).
cardiac hypertrophy (1 paper, 2022). "The increased expression of MAVS in TAC-induced cardiac hypertrophy may be explained by compensated mitochondrial biogenesis to meet the requirements for maintaining a certain cardiac output." (PMID 35844503, 2022). "Recently, it was reported that MAVS acted as downstream of nucleotide-binding oligomerization domain-containing protein 1/receptor-interacting protein 2 (NOD1/RIP2) to promote cardiac hypertrophy following pressure overload induced by transverse aortic constriction (TAC)." (PMID 35844503, 2022). "Differing from the upregulation of MAVS in TAC or Ang II-induced cardiac hypertrophy, MAVS was downregulated in LPS, IR or 5/6Nx-induced non-hypertrophic cardiac dysfunction." (PMID 35844503, 2022).
cervical intraepithelial neoplasia (1 paper, 2019). "The promoter methylation levels in cGAS, MAVS, and TRAF3 genes are higher in CPL than in control, indicating that hypermethylation might be an early event in the progression of cervical intraepithelial neoplasia (CIN)." (PMID 31803230, 2019).
cervical neoplasm (1 paper, 2019). "Viral infection of the host can trigger innate immune responses, and previous studies have revealed that cyclic GMP-AMP synthase (cGAS)/STING and RIG-I/MAVS pathways play important roles in host innate immunity against HPV-induced precursor lesions and invasive cancer of the uterine cervix." (PMID 31803230, 2019).
cholangiocarcinoma (1 paper, 2024). A carcinoma that arises from the intrahepatic biliary tree (intrahepatic cholangiocarcinoma) or from the junction, or adjacent to the junction, of the right and left hepatic ducts (hilar cholangiocarcinoma). "To gain a deeper understanding of the relevance and underlying mechanisms of the innate immune pathway in cholangiocarcinoma, we investigated the expression levels of DDX58, MAVS, C6orf150, TMEM173, IKBKE, TBK1, and IRF3 in different cell types using the TISCH2 database." (PMID 38817870, 2024). "Immunohistochemical results revealed that the expression of RIG-I, MAVS, cGAS, IRF3, MDA5, IFIT2, and IRF7 was significantly higher in liver tissue slices from patients with cholangiocarcinoma than in the control group." (PMID 38817870, 2024). "Tissue samples from the HPA database were analyzed to determine the functions of DDX58, MAVS, C6orf150, TMEM173, IKBKE, TBK1, and IRF3 in cholangiocarcinoma cells." (PMID 38817870, 2024).
chronic hepatitis C (1 paper, 2020). "The percentage of OCIAD1 cleavage varied widely among the 5 patients with chronic hepatitis C, ranging from 0 to 45% and correlating roughly with the serum viral loads as well as the percentage of MAVS cleavage previously observed in the same biopsy specimens." (PMID 32697788, 2020).
cutaneous melanoma (1 paper, 2025). A primary melanoma arising from atypical melanocytes in the skin. "Thus, our study identifies USP35 as a negative regulator of MAVS signaling, representing a potential immunosuppressive factor in cutaneous melanoma." (PMID 40016186, 2025).
endothelial dysfunction (1 paper, 2020). In vascular diseases, endothelial dysfunction is a systemic pathological state of the endothelium (the inner lining of blood vessels) and can be broadly defined as an imbalance between vasodilating and vasoconstricting substances produced by (or acting on) the endothelium. "PCV2 can activate RIG-I/MDA-5/MAVS/JNK signaling pathway to induce the production of endothelial-derived IL-8 in PIECs, which provides an insight into the further study of endothelial dysfunction and vascular system disorder caused by PCV2." (PMID 32727484, 2020).
foot and mouth disease (1 paper, 2021). A viral infectious disease that results in infection in cattle and swine, has material basis in foot-and-mouth disease virus, which is transmitted by contaminated fomites, or transmitted by ingestion of food contaminated with infected meat or animal products. "A recent study showed that the wild-type VP1 (83E) but not the mutant VP1 (83K) protein of foot and mouth disease (FMDV) subverts MAVS signaling by disrupting the interaction between MAVS and TRAF3101." (PMID 34782737, 2021).
hepatitis B virus infection (1 paper, 2021). A viral infection caused by the hepatitis B virus. "The latest research shows that hepatitis B virus infection directly binds to MAVS through lactate dehydrogenase-dependent lactic acid to prevent MAVS from mitochondrial aggregation and localization, thereby blocking the RLR signaling pathway." (PMID 33923929, 2021).
inflammatory brain diseases (1 paper, 2022). "Moreover, MAVS is reported to be a key signaling molecule and potential target for treatment in microglia-driven inflammatory brain diseases." (PMID 35850307, 2022).
iron deficiency (1 paper, 2023). "Next, MAVS Ser152 phosphorylation has been reported in a study that investigated the impact of iron deficiency in neuronal cells." (PMID 37238738, 2023). "Acute iron deficiency in HT-22, a hippocampal-derived neuronal cell line, resulted in the increased phosphorylation of proteins involved in inflammatory pathways, including MAVS." (PMID 37238738, 2023).
latent infection (1 paper, 2010). "By contrast, γHV68 latent infection as characterized by viral genome frequency, persistent lytic replication, and reactivation was similar in splenocytes of MAVS+/+ and MAVS−/− mice at 16 and 45 d.p.i.." (PMID 20686657, 2010). "The specific roles of MAVS in lytic replication and MyD88 in latent infection are consistent with their distinct functions in innate immune responses of epithelial cells and immune cells, respectively." (PMID 20686657, 2010).
leishmaniasis (1 paper, 2021). Infectious disease that is transmitted through the bite of hematophagous female phlebotomine sand flies. "Additionally, we found that SFSV and L. major co-infection resulted in an exacerbation of leishmaniasis in vivo, and by using endosomal (Toll-like receptor) TLR3, and MAVS knock-out mice, deduced that SFSV’s hyperinflammatory effect was TLR3- and MAVS-dependent." (PMID 34310619, 2021).
leukemia (1 paper, 2016). A malignant (clonal) hematologic disorder, involving hematopoietic stem cells and characterized by the presence of primitive or atypical myeloid or lymphoid cells in the bone marrow and the blood. "This is the first demonstration of VDAC1 and MAVS over-expression in leukemia." (PMID 27078856, 2016).
lipid metabolism disorder (1 paper, 2022). "However, the underlying mechanism by which MAVS deletion causes lipid metabolism disorder remains unclear and requires further research." (PMID 35844503, 2022).
liver cancer (1 paper, 2025). An epithelial or non-epithelial malignant neoplasm that arises from the liver. "For example, in liver cancer, overexpression of retinoic acid-inducible gene I (RIG-I) can promote M2 polarization of peritoneal macrophages in mice through the RIG-I/MAVS/TRAF1/NF-κB pathway, thus inducing apoptosis of liver cancer cells." (PMID 40131539, 2025).
liver disease (1 paper, 2025). "MAVS expression is induced in the liver of both animal models and people with MASLD as compared with those without liver disease." (PMID 38761407, 2025).
liver steatosis (1 paper, 2025). "Liver proteomic analysis of mice with genetically manipulated hepatic p63, a transcription factor that induces liver steatosis, revealed MAVS as a target downstream of p63." (PMID 38761407, 2025).
memory impairment (1 paper, 2020). "Inducing ERV activation in the mouse brain causes significant hippocampus-related memory impairment accompanied by robust activation of antiviral immune response mediated through Irf7; the pathology is attenuated in mice lacking cytosolic viral RNA sensor protein MAVS." (PMID 33101276, 2020).
mesothelioma (1 paper, 2022). A usually malignant and aggressive neoplasm of the mesothelium which is often associated with exposure to asbestos. "Basal ISG expression was higher in the mesothelioma cells compared with the mesothelial cells, and it was significantly decreased by ruxolitinib treatment or MAVS silencing." (PMID 36467966, 2022).
osteosarcoma (1 paper, 2013). A usually aggressive malignant bone-forming mesenchymal neoplasm, predominantly affecting adolescents and young adults. "Consistent with our model that LUBAC is not a negative regulator of MAVS signaling, tetracycline-inducible knockdown of HOIP in the human osteosarcoma cell line U2OS modestly inhibited the activation of IRF3 and induction of IFNβ by VSV." (PMID 23951545, 2013).
periodontitis (1 paper, 2025). An acute or chronic inflammatory process that affects the tissues that surround and support the teeth. "ROS production in response to LPS also activate the NLRP3 inflammasome by inducing OS‐related proteins like TXNIP and MAVS, which further drive periodontitis progression." (PMID 41298339, 2025).